RELA (RELA proto-oncogene, NF-kB subunit)
Diseases named in the same sentence as RELA in open-access papers (continued):
Sharing a sentence is not in itself a finding about the gene and the disease.
colorectal tumor (2 papers, 2021). "At the mechanic level, RelA/NF-κB plays a crucial role in colorectal tumor–related processes such as angiogenesis, cell proliferation, apoptosis, autophagy, and metastasis." (PMID 34867383, 2021).
depression (2 papers, 2024 to 2025). "This has previously been part of a gene set of RELA target genes associated with depression prior to bariatric surgery." (PMID 40585350, 2025). "Five of these TFs, namely ETS1, TFAP2A, NFKB2, CTCF, and RELA, are significantly deregulated in the blood samples of depression patients compared to controls (GSE217811 and GSE23848)." (PMID 38256187, 2024).
diabetic nephropathy (2 papers, 2017 to 2025). "In addition, the nephroprotection of SIRT1 in diabetic nephropathy is mediated by deacetylation of some transcription factors, including FoxO, RelA/NF-kβ, STAT-3, and PGC-1α/PPARγb, etc., and the higher activity of SIRT1 exerts the renal protective effect for diabetic kidney disease." (PMID 40649025, 2025).
endometriosis (2 papers, 2021 to 2023). The growth of functional endometrial tissue in anatomic sites outside the uterine body. "Therefore, by targeting RELA and altering the expression level of its downstream protein (COX-2), the decrease and increase of miR-182 in eESCs result in an increase and a decrease in inflammation in the endometriosis microenvironment, respectively." (PMID 37675122, 2023).
Endotoxemia (2 papers, 2016 to 2022). "Aqp9-/- knockout mice subjected to endotoxemia also showed reduced iNOS expression (and NO formation) and COX-2 expression, secondary to a reduced expression/activation of NF-ĸB RelA/p65 in the kidney, aorta, liver, and heart compared to wild-type mice induced with LPS." (PMID 35774785, 2022).
epilepsy (2 papers, 2011 to 2022). A brain disorder characterized by episodes of abnormally increased neuronal discharge resulting in transient episodes of sensory or motor neurological dysfunction, or psychic dysfunction. "Our results showed that the expression level of RELA was higher in the epilepsy group." (PMID 36138892, 2022). "The nomogram, using RELA, PRKAB1, TNFRSF1A, CAMKK2, and CPT1B, was next confirmed as a reliable predictive model for epilepsy that would bring patients a net clinical benefit when the threshold probability ranged from 0.1 to 1.0." (PMID 36138892, 2022).
fibrosis (2 papers, 2020 to 2023). the formation of excess fibrous connective tissue in an organ or tissue in a reparative or reactive process. "In contrast to its dual effects on pathogenesis and protection of intestinal inflammation, CMA inhibits EMT progression against intestinal fibrosis by downregulating NF‐κB (p65/RelA) signaling." (PMID 37655052, 2023).
HIV-1 infection (2 papers, 2024 to 2025). The type species of lentivirus and the etiologic agent of acquired immunodeficiency syndrome (AIDS). "Finally, VLP delivery of Vpr and HIV-1 infection shows that incoming virion-associated Vpr is sufficient to induce DNA damage and activate RelA/NF-κB transcription." (PMID 39269169, 2024).
hyperlipidemia (2 papers, 2024).
Hypertension (2 papers, 2020 to 2024). The presence of chronic increased pressure in the systemic arterial system. "For example, puerarin can have an effect on 45 targets, such as VEGFA, PTGS2, AR, PPARG, and RELA, when treating hypertension." (PMID 32265716, 2020). "Our analyses showed that TNF, HSP90AA1, NFKB1, PPARG, SIRT1, PTGS2, and RELA might be α-MG’s potential therapeutic targets for hypertension, laying groundwork for further investigation into its pharmacological mechanisms and clinical uses." (PMID 39592923, 2024). "The results indicate that in the Ang II-induced hypertension group, the expression levels of TNF, NFKB1, MAPK3, PTGS2, and RELA were markedly elevated compared to the control group, while the expression levels of HSP90AA1, HSP90AB1, PPARG, SIRT1, MAPK1, and PRKCA were significantly decreased." (PMID 39592923, 2024).
Immunodeficiency (2 papers, 2015 to 2024). Failure of the immune system to protect the body adequately from infection, due to the absence or insufficiency of some component process or substance. "Thus, RELA controlled different aspects of human CD8+ T cell biology, suggesting a CD8+ T-cell-intrinsic role for RELA in the immunodeficiency features detected in patients with RELA LOF." (PMID 38504985, 2024). "NF-κB is a heterodimeric complex of RelA and p50 subunits that interact with the DNA, regulating the expression of several genes; its dysregulation can trigger diverse diseases including inflammation, immunodeficiency, and cancer." (PMID 25615602, 2015).
influenza (2 papers, 2021 to 2022). An acute viral infection of the respiratory tract, occurring in isolated cases, in epidemics, or in pandemics; it is caused by serologically different strains of viruses (influenzaviruses) designated A, B, and C, has a 3-day incubation period, and usually lasts for 3 to 10 days. "Transcription factors predicted to function upstream of the intersection of Primula and influenza-associated gene terms indicated the influence of RelA/NF-κB." (PMID 36558964, 2022).
laryngeal carcinoma (2 papers, 2017 to 2024). Carcinoma that arises from the laryngeal epithelium. "Overexpression of RelA and P50 has been previously reported in laryngeal carcinoma and has been linked to tumor progression, therapy response, and prognosis, but the potential role of RelB as a biomarker of progression and survival is still under investigation." (PMID 29371965, 2017). "Using Cox regression analyses and tumor stage, local extent, grade and RelA/RelB immunoreactivity, we develop a new score that can independently predict survival of patients with laryngeal cancer." (PMID 29371965, 2017).
latent infection (2 papers, 2014 to 2024). "It was hypothesized that deletion of relA is critical for successful establishment of a persistent infection and that deletion of relA alters expression of antigenic and enzymatic factors essential for establishment of a latent infection." (PMID 24860792, 2014).
lymph node metastases (2 papers, 2005 to 2015). "In addition, we have detected high levels of nuclear RelA staining in lymph node metastases and in patients who developed bone metastases." (PMID 16205698, 2005). "Using multiple logistic regression, we identified that tumor RelB expression was an independent predictor of lymph node metastasis, and tumor P50 was an independent predictor of TNM6 stage IIB or higher, whereas tumor RelA was an independent predictor of inflammatory infiltration." (PMID 26147201, 2015).
measles (2 papers, 2017 to 2024). A highly contagious viral infection caused by the measles virus. "RELA (transcription factor p65), a subunit of the NF-κB complex, is implicated in both of the measles and PD-L1 pathways, mediating inflammatory responses and apoptosis." (PMID 39366989, 2024).
meningococcal disease (2 papers, 2015 to 2019). "We applied this method to meningococcal disease susceptibility, using the DNA binding pattern of RELA – a NF-kB subunit, master regulator of the response to infection – under bacterial stimuli in nasopharyngeal epithelial cells." (PMID 31061469, 2019). "It is worth noting that alteration of NF-κB was selective to p65/RelA subunit because expression of the p50/NF-κB1 subunit was not affected by meningococcal infection in either fraction (bottom blots)." (PMID 26241037, 2015).
metabolic syndrome (2 papers, 2019). A cluster of metabolic risk factors for CARDIOVASCULAR DISEASES and TYPE 2 DIABETES MELLITUS. "Finally, eleven CpG sites were associated with metabolic syndrome: cg08862778 (MTOR), cg11322849 (INS), cg07199894 (ULK1), cg11658986-cg04149773 (ADCY6), cg14862787-11301281 (CREB5), cg14844401-cg20300093 (ADCY5), cg01284192 (IGF1R) and cg08128650 (RELA)." (PMID 30926763, 2019).
myopericytoma (2 papers, 2017 to 2022). A usually slow growing, subcutaneous nodular neoplasm arising from myopericytes. "In particular, Antonescu and colleagues detected SRF rearrangements in eight cases of myofibroma/myopericytoma (among which six cases had identical SRF::RELA fusions) displaying a significant downregulation of SRF mRNA." (PMID 36421692, 2022).
ovarian serous carcinoma (2 papers, 2010 to 2012). "NF-κB (RelA/p65) is overexpressed in advanced-stage metastatic serous ovarian carcinoma, and its localization to the nucleus is associated with poor PFS." (PMID 22481932, 2012).
ovarian tumors (2 papers, 2010 to 2022). "This included genes in the NFkB pathway (e.g., NKFBIA, NKFBIE, TRAF2, RELA), which were downregulated among ovarian tumors from patients with greater lifetime ovulatory years." (PMID 35562768, 2022). "Proteomic analysis identified RELA and STAT5 as two major proteins associated with carboplatin resistance in ovarian tumors." (PMID 20585448, 2010).
Parkinson disease (2 papers, 2015 to 2024). A progressive degenerative disorder of the central nervous system characterized by loss of dopamine producing neurons in the substantia nigra and the presence of Lewy bodies in the substantia nigra and locus coeruleus. "A defect of c-Rel activity, associated with higher RelA activation, reduces SNc resilience to aging hereby leading to a late-onset form of parkinsonism." (PMID 26042083, 2015). "According to the target gene information from PubChem, in a Parkinson’s disease cell model, berberine inhibits the activation of the NF-κB pathway by modulating the LINC00943/miR-142-5p/KPNA4 axis, thereby reducing the nuclear translocation of the transcription factor p65 (RELA)." (PMID 39221152, 2024).
renal carcinoma (2 papers, 2021 to 2025). A carcinoma arising from the epithelium of the renal parenchyma or the renal pelvis. "In renal cancer models, neferine treatment induces apoptotic cell death through suppression of the NF-κB signaling pathway, mediated by caspase-dependent cleavage of the p65 (RelA) subunit." (PMID 41154606, 2025). "Similar results were also obtained in the NUC-7738–treated renal cancer cell lines 786-O (IC50 = 13 μmol/L) and UM-RC-2 (IC50 = 4 μmol/L) when fluorescence stained for intracellular RELA (p65)." (PMID 34497073, 2021).
renal cell carcinoma (2 papers, 2018 to 2023). "One study demonstrated that RelA/p65 could bind to the promoter of miR-452-5p and induce its expression in metastatic renal cell carcinoma, subsequently contributing to renal cell carcinoma invasion and metastasis." (PMID 37175530, 2023).
thyroid cancer (2 papers, 2023). "Although RELA and NFKB1 have not been directly linked to the development of thyroid cancer, the protein has been implicated in the development of other types of cancer." (PMID 37954148, 2023). "In summary, while RELA and NFKB1 have been shown to play a role in the development of various types of cancer, their specific function in thyroid cancer development remains unclear." (PMID 37954148, 2023).
acute pancreatitis (1 paper, 2018). An acute inflammatory process that leads to necrosis of the pancreatic parenchyma. "And the excessive activation of RELA can raise gene expression related to a variety of inflammatory responses in the occurrence and development process of acute pancreatitis, causing large numbers of cytokines and inflammatory mediators being involved in the inflammatory process of AP." (PMID 30671125, 2018).
airway hyperresponsiveness (1 paper, 2024). "Corn oil or TMX-treated/RelA-depleted [RelA knockdown (KD)] mice were repetitively exposed to airway HDM challenges to induce airway hyperresponsiveness (AHR)." (PMID 38713619, 2024).
Airway obstruction (1 paper, 2021). Obstruction of conducting airways of the lung. "This conclusion comes from studies where inhibition of NFκB/RelA signaling in bronchiolar small airway cells blocks RSV-induced inflammation and airway obstruction in vivo." (PMID 34765643, 2021).
alcoholism (1 paper, 2019). "Seven nodes including JUN, FOS, RELA, MAPK1, ATF2, HRAS, and CREB1 in the backbone are the recorded genes of alcoholism, amphetamine addiction, or cocaine addiction in the KEGG pathways." (PMID 30899073, 2019).
alopecia (1 paper, 2025). Hair loss usually from the scalp. "In addition, the RelA cKO mice developed alopecia characterized by hair loss at this stage." (PMID 40766184, 2025).
angiosarcoma (1 paper, 2016). A malignant tumor arising from the endothelial cells of the blood vessels. "For example, in human hemangioma and angiosarcoma lesions, high levels of RelA and strong activation of the NF-λB/IL-6/STAT3 signaling axis has been previously reported." (PMID 27105514, 2016).
autoimmune lymphoproliferative syndrome (1 paper, 2024). Autoimmune lymphoproliferative syndrome (ALPS) is a rare, inherited disorder characterized by non-malignant lymphoproliferation, multilineage cytopenias, and a lifelong increased risk of Hodgkin's and non-Hodgkin's lymphoma. "Heterozygous LOF mutations in RELA cause chronic mucocutaneous ulceration and autoimmune lymphoproliferative syndrome (ALPS)." (PMID 38772735, 2024).
autoimmune uveitis (1 paper, 2019). An autoimmune form of uveitis (disease). "According to our results, KS23 may also act to ameliorate autoimmune uveitis via an anti-inflammatory response induced by the deacetylation of RELA/p65, following the upregulation of AMPK and SIRT1 expression." (PMID 31883532, 2019).
bipolar disorder (1 paper, 2021). A disorder of the brain that causes unusual shifts in mood, energy, activity levels and the ability to carry out day-to-day tasks. "NF-κB2, RelA, and cRel mRNA levels were higher in 71%, 69 and 71%, respectively, of bipolar disorder subjects relative to their matched comparison subjects." (PMID 33436571, 2021). "Transcript levels for NF-κB2, RelA, and cRel were strongly correlated with each other, which suggests the presence of higher levels of functional NF-κB heterodimers in the same bipolar disorder subjects." (PMID 33436571, 2021). "First, we found that bipolar disorder subjects have higher mRNA levels for three NF-κB family members, NF-κB2, RelA, and cRel, relative to unaffected comparison subjects." (PMID 33436571, 2021). "Furthermore, IFITM1 mRNA levels were correlated with mRNA levels for IL-1R, TNFR, NF-κB2, and RelA across all subjects (all r ≥ 0.41, all p ≤ 0.004) and in bipolar disorder subjects alone (all r ≥ 0.60, all p ≤ 0.0001)." (PMID 33436571, 2021). "Furthermore, both IL-1R and TNFR mRNA levels were each correlated with mRNA levels for NF-κB2, RelA, and cRel across all subjects (all r ≥ 0.56, all p < 0.00001), in bipolar disorder subjects alone (all r ≥ 0.73, all p < 0.00001), and in comparison subjects alone (all r ≥ 0.45, all p ≤ 0.001)." (PMID 33436571, 2021). "We first determined whether mRNA levels for family members of the NF-κB transcriptional complex, including NF-κB1, NF-κB2, and other members of the NF-κB family that contain Rel homology domains including RelA, RelB, and cRel, were elevated in the PFC of bipolar disorder subjects." (PMID 33436571, 2021).
breast invasive carcinoma (1 paper, 2024). "The analysis of the clinical stages of patients with breast invasive carcinoma indicated that the BAX, BCL2L1, CASP8, CASP9, RELA, and NFKBIA gene expression levels were higher in stages 3 and 4 for all BRCA patients, and in stage 4 for BRCA-LumA patients, than in other clinical stages." (PMID 38542508, 2024).
cardiac hypertrophy (1 paper, 2021). "Congruently, several reports suggest that NF-κB inhibition suppresses cardiac hypertrophy although a direct role of macrophage RelA has yet to be established in vivo." (PMID 33898415, 2021).
cervical intraepithelial neoplasia (1 paper, 2025). "The results showed that the DEGs regulated by RELA during cervical intraepithelial neoplasia (CIN1, CIN3, and HSIL) stages were mainly enriched in interleukin-related pathways and inflammatory response pathways, which are associated with immune regulation." (PMID 40141137, 2025).
cholangiocarcinoma (1 paper, 2019). A carcinoma that arises from the intrahepatic biliary tree (intrahepatic cholangiocarcinoma) or from the junction, or adjacent to the junction, of the right and left hepatic ducts (hilar cholangiocarcinoma). "An early study investigated the expression of NF-κB in liver fluke-associated cholangiocarcinoma and showed that NF-κB family of transcription factors (p50, p52 and RelA) were highly expressed in CCA patient tissues, while the expression in normal bile duct epithelium was absent." (PMID 31349670, 2019).
cholesteatoma (1 paper, 2012). A pathologic process characterized by the proliferation of keratinizing squamous epithelium resulting in the accumulation of keratin and cells in the middle ear and/or mastoid. "A down-regulation of cIAP1 (BIRC2) was observed, whereas p65 (RELA), cFlip (CFLAR) and Bcl-2 show similar expression levels in cholesteatoma and external auditory skin samples." (PMID 23285167, 2012).
choriocarcinoma (1 paper, 2012). An aggressive malignant tumor arising from trophoblastic cells. "The 11q13.1 gain, exclusively contributed by de novo choriocarcinomas, contained RELA, a nuclear transcription factor NF-kappa-B complex subunit." (PMID 22253721, 2012).
chronic obstructive pulmonary disease (1 paper, 2023). A chronic and progressive lung disorder characterized by the loss of elasticity of the bronchial tree and the air sacs, destruction of the air sacs wall, thickening of the bronchial wall, and mucous accumulation in the bronchial tree. "In chronic obstructive pulmonary disease (COPD), monocytes in lung tissue induce the transcription of PRMT7 through the NF-κB/RelA signaling pathway." (PMID 37699892, 2023).
CNS primitive neuroectodermal tumour (1 paper, 2021). "Additionally, we identified one RELA+ tumour among historically diagnosed CNS primitive neuroectodermal tumour samples." (PMID 34314101, 2021).
combined immunodeficiency (1 paper, 2025). A broad classification of inherited disorders presenting at birth that affect both the cell-mediated and humoral aspects of the immune response. "Although classified as combined immunodeficiency, patients with RelA deficiency typically do not exhibit pronounced susceptibility to infections." (PMID 40134438, 2025).
cryptosporidiosis (1 paper, 2024). Intestinal infection with organisms of the genus Cryptosporidium. "In order to investigate the mechanism of oxymatrine in treating cryptosporidiosis, we constructed a target-KEGG network and identified the top 5 involved genes, namely RELA, AKT1, TNF, CASP3, and IL-6." (PMID 38914662, 2024).
cutaneous abscesses (1 paper, 2017). "Promoter fusions of relA or spoT to a bioluminescence reporter gene revealed that both genes were expressed during the formation of cutaneous abscesses in mice." (PMID 29021784, 2017).
diabetic retinopathy (1 paper, 2020). "PARP1 was shown to promote nuclear translocation of RelA (p65) in T. cruzi-infected cardiomyocytes and to enhance NF-κB/AP-1 binding to the MMP9 promoter sequence in diabetic retinopathy and JNK-dependent activation of AP-1 in murine fibroblasts." (PMID 33172999, 2020).
endometrial cancer (1 paper, 2022). Primary or metastatic malignant neoplasm involving the endometrium (mucous membrane that lines the endometrial cavity). "Invasion and migration of endometrial cancer cells was also inhibited via IL-37b-mediated suppression of RelA, however it did not affect EMT." (PMID 35328833, 2022).